PRKCI (protein kinase C iota)
Diseases named in the same sentence as PRKCI in open-access papers (continued):
Sharing a sentence is not in itself a finding about the gene and the disease.
pheochromocytoma (1 paper, 2019). "Similarly, mutations only associated with pheochromocytoma severely affect the DGKZ, PRKCI, PRKCD and PRKCZ kinase binding interfaces, further suggesting a link between hypoxia sensing and phosphorylation-mediated signaling." (PMID 30943211, 2019).
Retinal dysplasia (1 paper, 2022). Abnormal growth and differentiation, structure and appearance of the retina present from birth. "Retinal dysplasia is more severe in Tvrm323 mice, which express variants of two apiocobasal polarity proteins, PRKCI and CRB1, when compared to B6 rd8 mice, in which only CRB1 is disrupted." (PMID 35675330, 2022). "Deficits in mouse CRB1, CRB2, CRB1 and CRB2 combined, MPP5, and PRKCI have similar effects, supporting the hypothesis that defects in apicobasal polarity cause retinal dysplasia." (PMID 35675330, 2022).
tongue squamous cell carcinoma (1 paper, 2015). A squamous cell carcinoma that arises from the tongue. "MiR-219 regulates PRKCI and accordingly inhibits the proliferation of human tongue squamous cell carcinoma." (PMID 26231038, 2015).
tumor (31 papers, 2010 to 2025). "This cancer-specific expression pattern suggests the existence of a therapeutic window, allowing for selective inhibition of PRKCI in tumor cells with potentially minimal toxicity to normal tissues." (PMID 41188443, 2025). "Both the expression of RIPK2 and PRKCI in tumor tissues decreased in mice of the RIPK2KO group than mice of the RIPK2Scramble group." (PMID 37016317, 2023). "Tumor cell-derived exosomal circ-PRKCI promoted the proliferation, migration, and invasion of RCC cells, while inhibiting their apoptosis." (PMID 36612120, 2022). "Circ-PRKCI is a novel ncRNA discovered in recent years and has been confirmed to participate in tumor progression by acting as miRNA sponges." (PMID 36612120, 2022). "Recently, amplification of CCNE1 or PRKCI has been reported to promote HGSOC, by enhancing an immunosuppressive tumor microenvironment in the case of PRKCI amplification, conferring chemoresistance in OV." (PMID 36201246, 2022). "Our study is the first to report the potential mechanisms of tumor cell-derived exosomal circ-PRKCI in RCC." (PMID 36612120, 2022). "Circ-PRKCI is a novel circRNA discovered in recent years, and has been confirmed to participate in tumor progression by acting as an miRNA sponge." (PMID 36612120, 2022). "In ESCC, miR-3680-3p is expressed at a low level and plays a role in inhibiting tumor growth, while circ-PRKCI can bind to miR-3680-3p and reverse its regulatory effect." (PMID 33627631, 2021). "PRKCI (protein kinase C iota) mRNA and protein expression levels were up-regulated in ESCC compared with normal tissue and the protein expression levels associated with larger tumour size, high grade and invasion." (PMID 32429269, 2020). "In mice, PRKCI depletion gave rise to smaller tumours and less lung metastases than in the control group." (PMID 32429269, 2020). "In order to determine the effect of ATM on in vivo tumor growth, PRKCI-knockdown and PRKCI-overexpressing CCOC cells were intraperitoneally injected into athymic nude mice and the mice were administrated with 20 mg/kg/day for 14 consecutive days." (PMID 29228547, 2017). "Mice with KOC-7c PRKCI-knockdown cells showed significantly smaller tumor masses than mice with KOC-7c control cells." (PMID 29228547, 2017). "Conversely, high PRKCI expression level correlated with poor clinical outcome of CCOC patients and expression of PRKCI drives multiple important biologic properties including tumor cell migration, invasion and in vivo growth." (PMID 29228547, 2017). "qRT-PCR further validated PRKCI overexpression in CCOC tumor specimens over normal ovarian surface epithelium samples." (PMID 29228547, 2017). "Elevated PRKCI copy number was found in 20 out of 27 CCOC tumor specimens when compared with peripheral blood cell DNA as normal reference." (PMID 29228547, 2017). "ATM treatment was found to suppress tumor growth in mice with PRKCI overexpressing cells, including mice with KOC-7c control cells and PRKCI overexpressing ES2 and TOV21G cells." (PMID 29228547, 2017). "The activation of MEK/ERK and Akt signaling pathways is required for PRKCI inducing tumor growth as tumor growth in PRKCI overexpressing cells were significantly suppressed by the MEK/ERK and Akt inhibitors (PD98059 and perifosine)." (PMID 29228547, 2017).
tumor (continued). "Pancreatic PRKCI knockdown significantly increased pancreatic immune cell infiltrations acinar cell DNA damage, apoptosis, and promoted KrasG12D mediated pancreatic intraepithelial neoplasia, promoting tumor growth." (PMID 37396042, 2023). "PKCι maintains PRKCI copy number gains in cancer cells and contributes to tumor initiation." (PMID 35626066, 2022). "Of these, PRKCI is one of the most frequently amplified and overexpressed genes and its expression induced cancer cell proliferation and migration/invasion in vitro as well as tumor growth in vivo." (PMID 29228547, 2017). "In addition, we have investigated the effect of PRKCI on CCOC in vivo tumor growth, using an orthotopic mouse model." (PMID 29228547, 2017). "ATM can specifically suppress tumor growth in PRKCI overexpressing CCOC cells." (PMID 29228547, 2017). "We also explored the protein expression level of PRKCI and ITGA2 in the Human Protein Atlas (HPA) database, and found that the expression level of both genes were significantly higher in tumor tissue than in normal tissues." (PMID 37386391, 2023). "Our present data revealed that PPP1R14C, together with PRKCI, and PP1, maintained the phosphorylation of GSK3β at Ser9, which accelerated tumour proliferation and metastasis in TNBC." (PMID 35090098, 2022). "It has been found that the circular RNA for protein kinase C (circ-PRKCI) is overexpressed in ESCC, and overexpressed circ-PRKCI can promote the proliferation and migration of tumor cells." (PMID 33627631, 2021). "The most crucial finding in this study was that PKC isoenzymes are robust biomarkers for the tumor immune status, PRKCB, PRKCH, and PRKCQ as stimulators, while PRKCI and PRKCZ as inhibitors in most cancers." (PMID 35174160, 2021). "Fxr1 can also form a complex with PRKCI and ECT2, which controls cell proliferation/cell survival and links Fxr1 expression with human tumours; of note, elevated Fxr1 mRNA levels correlate with poor prognosis." (PMID 29142209, 2017). "Targeting PRKCI by small molecule inhibitor, sodium aurothiomalate (ATM), significantly reduced the in vivo tumor growth and may be a new therapeutic strategy to improve the treatment of CCOC." (PMID 29228547, 2017). "In addition, mice with PRKCI-overexpressing ES2 and TOV21G cells showed significantly larger tumor masses than mice with ES2 and TOV21G control cells." (PMID 29228547, 2017).
cancer (25 papers, 2011 to 2025). A tumor composed of atypical neoplastic, often pleomorphic cells that invade other tissues. "The overexpression of PRKCI was associated with poor outcomes in patients with gastric and other cancers." (PMID 33363566, 2020). "Interestingly, PRKCI’s expression promotes an immune suppressive microenvironment that contributes to poor prognosis in human cancers, and elevated PRKCI expression is associated with immune-suppressive TME and poor prognosis in various cancers." (PMID 38234757, 2023). "Third, the diagnostic performance of serum exosomal circ-PRKCI has been explored in our center with limited sample size, which requires further validation in multiple centers with larger sample sizes with various cancer types." (PMID 36612120, 2022). "Similar to PRKCZ, PRKCI belongs to the atypical protein kinase C family group, and it has been implicated in the establishment of cell polarity, motility, proliferation, and survival of cancer cells." (PMID 25874946, 2015). "Since PRKCI was overexpressed in many cancer types, it had a high proportion of CNGs, and these gains were strongly associated with PRKCI expression so that CNGs might be the primary up-regulatory mechanism of PRKCI in diverse cancer types." (PMID 35174160, 2021). "Protein kinase C iota (Prkci) is an atypical protein kinase C family member known to play significant roles in cancer progression." (PMID 40840329, 2025). "Together, these findings support the feasibility of targeting PRKCI in cancer treatment, while also underscoring the need for further investigation into its physiological roles and on-target safety in preclinical settings." (PMID 41188443, 2025). "Protein kinase C iota (Prkci) is an atypical protein kinase known for its oncogenic roles in various cancers; however, its function in CRC angiogenesis remains largely unexplored." (PMID 40840329, 2025). "Emerging studies have underscored the pivotal importance of PRKCI in triggering Akt-mTOR activation within cancerous cells, revealing its potential as a crucial factor in cancer development and progression." (PMID 39015499, 2024). "Through the exoRBase database, we screened for circRNAs differentially expressed in plasma exosomes of various cancers and found that circ-PRKCI (circbase ID: hsa_circ_0067934) was upregulated in plasma exosomes of RCC patients." (PMID 36612120, 2022). "PRKCI and PRKCZ expressions were negatively correlated with most TILs in most cancer types (except PRKCI in ACC and OV; PRKCZ in ACC, SARC SKCM, had a positive correlation)." (PMID 35174160, 2021). "The lncRNA GPRC5D-AS1 with CNVs driving the dysregulation of downstream cancer genes such as PRKCI, SEM1, TBL1XR1, IMPACT, and RPL22L1 further disturbed the activities of NOTCH signaling pathway that is usually inactivated in LUSC." (PMID 34925461, 2021). "At the same time, a high level of PRKCI was predictive of inadequate response to HLA-dependent immunotherapies in most cancers." (PMID 35174160, 2021). "In several carcinomas, the PRKCI gene is documented to be amplified, even if PKC-ι overexpression does not necessarily associate with gene amplification." (PMID 33525953, 2021). "Within these genes, AKAP9, CENPE, PRKCI, RDX, RECQL, and USO1 have also been reported to be associated with cancer progression." (PMID 31426369, 2019). "RNA-seq analyses found protein kinase C iota (PRKCI) to be over expressed in patient neutrophils relative to neutrophils from cancer-free individuals." (PMID 28721376, 2016). "PRKCI is a serine/threonine kinase in the NF-KB pathway and previous tissue microarray data validated this gene as a potential novel cancer driver gene." (PMID 24874471, 2014). "For a comprehensive overview of PRKCI-related circRNAs in multiple cancer types, we explored their expression patterns in the exoRBase database and found that hsa_circ_0067934 (hereafter referred as circ-PRKCI) was upregulated in the plasma exosomes of RCC patients." (PMID 36612120, 2022).
cancer (continued). "However, some cancers showed a lowered level of PRKCI (GBM, KICH, HIRC, THCA) and PRKCG (GBM, THCA)." (PMID 35174160, 2021). "Depending on our results, PRKCI, PRKCD, and PRKCZ associated-CNAs were driving their expressions in most cancers (except for PRKCI in DLBC, KICH, LAML, THCA, and THYM; PRKCD in GBM, HNSC, LAML, LGG, THYM, and UCS; and PRKCZ in ACC, GBM, KICH, LGG, THCA, THYM, and UCS)." (PMID 35174160, 2021). "Methylation level and CNAs could drive the expression levels of some PKC members, especially PRKCI, whose CNGs are predicted to elevate their level in many cancer types." (PMID 35174160, 2021). "Therefore, PRKCI is considered an important target for cancer treatment." (PMID 33234130, 2020). "On the other hand, PRKCI elevated level was generally predicted to enhance the response to PD-L1 blocking-dependent immunotherapies in many cancers (except for ESCA, OV, and TGCT, in which PRKCI level was inversely correlated with PD-L1)." (PMID 35174160, 2021). "Collectively, the expression levels of PRKCI and PRKCG were elevated in most of the significantly compared cancers, while PRKCA, PRKCB, PRKCE, and PRKCQ tended to be downregulated among most cancer types." (PMID 35174160, 2021). "Cancer-related genes commonly amplified from 3q26 include PIK3CA, TBL1XR1, DCUN1D1, SOX2, MECOM, PRKCI, and TERC." (PMID 34436017, 2021). "As above reported, the amplification of chromosome 3q26 results in the co-amplification and co-expression of protein kinase C iota (PKCι) and SOX2 in LSQCC which cooperate to trigger and maintain cell-autonomous HH signaling in LSQCC cancer stem cells." (PMID 30060526, 2018).
kidney disease (2 papers, 2019 to 2022). "Combined with our data, it is conceivable that PRKCI plays a protective role in kidney diseases." (PMID 35869269, 2022).
infection (1 paper, 2020). The state of being infected such as from the introduction of a foreign agent such as serum, vaccine, antigenic substance or organism. "Transfection of LSCC cells with siRNAs targeting PRKCI (si-PRKCI) or infection with PRKCI overexpression lentiviruses (PRKCI-OE) changed PRKCI levels successfully." (PMID 33234130, 2020).
psychiatric disorder (1 paper, 2024). A disorder characterized by behavioral and/or psychological abnormalities, often accompanied by physical symptoms. "We identified dysregulations in four PKC genes—PRKCA, PRKCB, PRKCH, and PRKCI—known for their roles in mood regulation and stress response, crucial for neurodevelopment and linked to psychiatric disorders." (PMID 39238930, 2024).
PRKCI also shares sentences with these, for which no sentence is quoted: non-small cell lung carcinoma (2 papers); adenocarcinoma (1); alveolar rhabdomyosarcoma (1); bipolar disorder (1); chondrosarcoma (1); congenital megacolon (1); Ductal carcinomas (1); gastric cancer (1); glomerular diseases (1); gout (1); gynecological tumors (1); hyperlipidaemia (1); Hypertension (1); metastatic tumors (1); myocardial infarction (1); Nephrotic Syndrome types 1 (1); ovarian epithelial tumor (1); renal cell carcinoma (1); tongue cancer (1).